DTX2 (deltex E3 ubiquitin ligase 2)
Description:
E3 ubiquitin ligase that conjugates ubiquitin to ADP-ribosylated cysteine residues, independently of lysine side chains or free N-termini. For example, PARP7 generates an ADP-ribosyl degron within the DNA-binding domain of the androgen receptor (AR), which is recognized by DTX2 and targeted for proteasomal degradation. Functions in genome stability maintenance by acting as an ADP-ribosylation-dependent regulator of DNA double-strand break repair. Mechanistically, recognizes PARylated substrates generated in response to DNA damage and promotes their ubiquitination via its RING and DTC domains. Also regulates additional cellular pathways through ubiquitination of specific substrates. Acts as an E3 ubiquitin ligase for RNA demethylase FTO, promoting its ubiquitination and proteasomal degradation. In turn, regulates antitumor immune responses. Promotes 'Lys-27'-linked ubiquitination of TFRC, thereby modulating iron metabolism and inhibiting ferroptosis. In addition, promotes transcription of telomerase reverse transcriptase by mediating 'Lys-63'-linked ubiquitination of nuclear factor 1 C-type (NFIC) that stabilizes its binding on hTERT promoter.
Synonyms: KIAA1528; RNF58
Tractability: Small molecule: a structure with a bound ligand is known. PROTAC: ubiquitination databases record sites on it.
Gene: Protein-coding gene on chromosome 7 (76,461,656 to 76,506,471, forward strand). Ensembl gene ENSG00000091073.
Subcellular location: Chromosome; Cytoplasm; Nucleus
Subcellular location (Human Protein Atlas): Nuclear membrane; Nucleoplasm; Cytosol; Plasma membrane; Vesicles
Pathways (Reactome):
Signal Transduction: Activated NOTCH1 Transmits Signal to the Nucleus
Gene Ontology:
Molecular function: protein binding; ubiquitin protein ligase activity; zinc ion binding
Biological process: Notch signaling pathway; protein ubiquitination
Cellular component: cytosol; nuclear membrane; nucleoplasm; chromosome; cytoplasm; nucleus
Genetic constraint (gnomAD): Loss-of-function variants: 27 observed, 43.56 expected, observed/expected ratio (o/e) 0.62, 90% interval 0.46 to 0.86. The upper end of that interval is the gene's LOEUF score, 0.86, which puts it in group 3 of 6, group 1 being the genes least tolerant of losing a copy. Missense variants: 522 observed, 654.15 expected, observed/expected ratio (o/e) 0.8, 90% interval 0.74 to 0.86. Synonymous variants: 274 observed, 271.65 expected, observed/expected ratio (o/e) 1.01, 90% interval 0.91 to 1.12.
Homologues: Orthologues: chimpanzee DTX2 (98% identical), macaque DTX2 (96% identical), dog DTX2 (91% identical), pig DTX2 (91% identical), rabbit DTX2 (88% identical), guinea pig Dtx2 (88% identical), rat Dtx2 (85% identical), mouse Dtx2 (85% identical), tropical clawed frog dtx2 (51% identical), zebrafish dtx2 (49% identical). Paralogues in human: DTX1 (46% identical), DTX4 (45% identical), DTX3L (21% identical), DTX3 (17% identical).